KRTAP19-4 (keratin associated protein 19-4)
Description:
In the hair cortex, hair keratin intermediate filaments are embedded in an interfilamentous matrix, consisting of hair keratin-associated proteins (KRTAP), which are essential for the formation of a rigid and resistant hair shaft through their extensive disulfide bond cross-linking with abundant cysteine residues of hair keratins. The matrix proteins include the high-sulfur and high-glycine-tyrosine keratins.
Synonyms: KAP19.4
Tractability: No criterion of Open Targets' tractability assessment is met for any kind of drug.
Gene: Protein-coding gene on chromosome 21 (30,496,824 to 30,497,165, reverse strand). Ensembl gene ENSG00000186967.
Pathways (Reactome):
Developmental Biology: Keratinization
Gene Ontology:
Molecular function: protein binding
Cellular component: cytosol
Genetic constraint (gnomAD): Loss-of-function variants: 0 observed, 0.27 expected, observed/expected ratio (o/e) 0, 90% interval 0 to 1.87. That is too few expected variants to judge how well the gene tolerates losing a copy. Missense variants: 102 observed, 105.57 expected, observed/expected ratio (o/e) 0.97, 90% interval 0.82 to 1.14. Synonymous variants: 42 observed, 43.55 expected, observed/expected ratio (o/e) 0.96, 90% interval 0.75 to 1.25.